IL4 (interleukin 4)
Diseases named in the same sentence as IL4 in open-access papers (continued):
Sharing a sentence is not in itself a finding about the gene and the disease.
dermatitis (continued). "A study has showed that melatonin suppresses the development of AD-like dermatitis in DNFB-treated NC/Nga mice, reduces total serum IgE level, and decreases IL-4 and IFN-γ production by activated CD4+ T cells." (PMID 35163297, 2022). "In a mouse model of AD, topical melatonin treatment improved gross dermatitis severity, reduced epidermal hyperplasia and lymphocyte infiltration in the skin, and decreased IP-10, CCL27, IL-4, and IL-17 levels in superficial skin-draining lymph nodes." (PMID 35163297, 2022). "In our study, the levels of IL-4, TNF-α, INF-γ, and IgE in serum were reduced; meanwhile, the inflammation of back skin, the skin inflammation score, and the ear swelling of mice were alleviated after taking the TXS." (PMID 35646146, 2022). "Notably, the spontaneous dermatitis in WASp-deficient mice was dependent on IL-17 and not IL-4." (PMID 35265075, 2022). "In our study, we found that HB markedly suppressed mRNA expression of IL-4, IL-13, and the transcription factor GATA3 known to drive immune cells to produce a type 2 immune response in dermatitis skin tissue." (PMID 34531749, 2021). "Ethanol extracts of Ampelopsis brevipedunculata rhizomes inhibited an AD-like skin inflammation through downregulation of serum IgE levels and expression of TNF-α, interferon (IFN)-γ, IL-4, IL-13, and IL-31 in a BALB/c AD model." (PMID 33335525, 2020). "With the poor expression of IL4, the total IgE production in DNFB-induced dermatitis of NC/Nga is likely stimulated via an IL-4-independent mechanism." (PMID 29416104, 2018). "Moderate and high dosages of the TPL-nanoemulsion gels can significantly improve the symptoms of dermatitis/eczema inflammation and edema erythematic in mice ears and can reduce the expression of IFN-γ and IL-4." (PMID 29202753, 2017). "The expression levels of IL-1β, IL-4, IL-6, and TNF-α in peripheral blood positively correlate with the severity of dermatitis and may contribute to disease recurrence." (PMID 39748922, 2024). "During skin inflammation, proteolytic enzymes trypsin and tryptase signal pro-inflammatory factors through PAR-2, leading to the production of chemokines and cytokines like TNFα, IL-4, and TSLP." (PMID 37511138, 2023). "We analyzed outcomes changes in the symptoms of dermatitis assessed by SCORAD, skin severity, and itch severity, changes in the quality of life reported at the end of therapy, and changes of cytokines (IFN-γ, Serum IgE, IL-4)." (PMID 35978397, 2022). "In some mammalian species, prolonged exposure to OVA may lead to the development of dermatitis and infiltration of CD3+ T cells, eosinophils, and neutrophils, as well as increased mRNA levels of interleukin IL-4, IL-5, and IFN-γ." (PMID 35433509, 2022). "Our observations point to IL-17A, but not IL-4, contributing to the development and/or maintenance of the skin inflammation described in WAS−/− animals." (PMID 35265075, 2022). "We found that in DNCB-stimulated Balb/c mice, topical melatonin treatment improved gross dermatitis severity, reduced epidermal hyperplasia and lymphocyte infiltration in the skin, and decreased IP-10, CCL27, IL-4, and IL-17 levels in superficial skin-draining lymph nodes." (PMID 35163297, 2022). "In this regard, the lack of IL-17A is known to reduce skin inflammation and suppress IL-4 and IgE production." (PMID 36362286, 2022). "In addition, the expression level of filaggrin was reduced by C3A and GGRT treatment, and the expression levels of dermatitis-related proteins, including KLK7, PAR-2, TSLP, and IL-4, were markedly recovered." (PMID 34946332, 2021). "The lack of IL-17A reduced dermatitis and IL-4 production as well as IgE production, and its presence triggered the production of IL-4 by Th2 cells." (PMID 30304837, 2018). "Furthermore, although the expression of IL-4 mRNAs in skin was undetectable in control rats, DNCB-treatment induced their expression in dermatitis lesion." (PMID 28265582, 2017).
dermatitis (continued). "In our research, QP administration significantly inhibited the skin inflammation and the production of IgE and IL-4 as MF, but increased the level of tissue IFN-γ unlike MF." (PMID 24027597, 2013). "Thus, we hypothesize that IL-17 is a key cytokine in AD that exacerbates skin inflammation during host–Malassezia action and may be overexpressed with some inhibitory effect on TLSP, IFN-γ, and IL-4." (PMID 40309262, 2025). "All mice with oxazolone-induced dermatitis had a dramatic increase in IL-1β, IL-4, IL-6, IL-10, TNF-α, IFN-γ, IL-16, IL-17C, IL-17E, IL-17F, IL-21, IL-22, and MIP-3a, whereas the concentrations of IL-12p70, IL-2, IL-17A, and IL-23 were lower in dermatitis mice." (PMID 37889696, 2023). "From our current study, topical melatonin treatment improved the skin inflammation and thickening in a mouse model of AD, which is potentially due to regulation of inflammatory cytokines and chemokines including IP-10, MCP-1, CCL-27, and IL-4, and reduction of cytokine-induced cell proliferation." (PMID 35163297, 2022). "Mice lacking IL-17A exhibited reduced dermatitis together with less IL-4 and IgE production." (PMID 34531749, 2021). "In the absence of STAT6, required for signaling through the IL4 and IL13 receptor, these mice had undetectable IgE, but developed a similar dermatitis indicating that the IgE was not necessary for the development of the dermatitis." (PMID 32687504, 2020).
rheumatoid arthritis (91 papers, 2005 to 2026). A chronic, systemic autoimmune disorder characterized by inflammation in the synovial membranes and articular surfaces. "Is there any association of cytokine IL-17, IL-4, IL-6, and IL-12 gene polymorphisms with disease susceptibility and severity in rheumatoid arthritis patients in the Bangladeshi population?" (PMID 38344692, 2024). "For instance, a previous study demonstrated that the −590 C/T polymorphism of IL-4 promoter is associated with genetic susceptibility to rheumatoid arthritis." (PMID 25667655, 2015). "Rheumatoid arthritis (RA) is now suspected to be driven by pathogenic Th17 cells that secrete interleukin (IL)-17 and can be regulated by IL-4." (PMID 21294892, 2011). "In this study, we used LPS and IL-4 to induce macrophage to M1 and M2 macrophages to investigate the mechanisms underlying the therapeutic effects of IL-1β-hUCMSCs on macrophage polarization and macrophage apoptosis in rheumatoid arthritis." (PMID 37391581, 2023). "IL-4 levels are also associated with the development of early-stage of rheumatoid arthritis." (PMID 35153741, 2021). "IL-4-590 promoter polymorphism, a C-to-T base substitution, has been suggested to be associated with RA, especially with early pauciarticular juvenile rheumatoid arthritis." (PMID 24707478, 2014). "Recent research underscores IL-4’s dual role in rheumatoid arthritis (RA) pathogenesis and therapeutic potential." (PMID 41009491, 2025). "The expression of CCL-23 mRNA was found in monocytes stimulated with IL-1β and IL-4 and can also be detected in SFs from patients with rheumatoid arthritis." (PMID 40083631, 2025). "IL‐4 and IL‐10 are well‐known immunomodulatory cytokines that act as anti‐inflammatory mediators in degenerative joint diseases, including rheumatoid arthritis and osteoarthritis." (PMID 39931581, 2025). "IL-13 (and IL-4) belong to the T helper 2 (Th2) cytokine family and have been shown to play a role in downmodulating inflammatory responses in rheumatoid arthritis, induce macrophage polarization from a pro-inflammatory M1 to an anti-inflammatory M2 phenotype." (PMID 38585987, 2024). "Another study reported that HSP60 prevents inflammation-induced cell death in rheumatoid arthritis (RA) via secretion of anti-inflammatory cytokines IL-4 and IL-10 at the inflammation site in the bone." (PMID 38673794, 2024). "An imbalance between the proinflammatory cytokines and anti-inflammatory cytokines, such as IL-10 and IL-4, precipitates inflammatory disease conditions, including rheumatoid arthritis." (PMID 35248062, 2022). "For instance, nicotine treatment significantly increases Th2 differentiation in peripheral blood mononuclear cells (PBMCs) isolated from rheumatoid arthritis patients, as observed by an increase in IL-4 production and enhanced GATA3 expression." (PMID 35003121, 2021). "Anastrozole increased the production of proinflammatory cytokines like IFN-γ, IL-12 and decreased IL-4 and IL-10 cytokine secretion in an animal model that simulates human rheumatoid arthritis." (PMID 33530456, 2021). "In the animal model of rheumatoid arthritis (RA), helminth therapy with S. mansoni and S. japonicum showed attenuation of disease severity via up-regulation of IL-4 and IL-10." (PMID 34451389, 2021). "In the Rheumavax clinical trials for rheumatoid arthritis, tDC generated in GM-CSF+IL-4 and the NF-κB inhibitor Bay 11-7082, exhibited lower CD40, and HLA-DR on a per cell basis." (PMID 30787930, 2019). "The modulation of IL-4 levels by resveratrol it is an important finding regarding the progression of rheumatoid arthritis." (PMID 30281626, 2018). "In contrast, IL-13 is expressed in rheumatoid arthritis synovial fluid and synovial fluid macrophages and resembles many functions of IL-4." (PMID 15743487, 2005).
rheumatoid arthritis (continued). "CD40L and IL-4 significantly upregulate human leukocyte antigen (HLA)-E and total HLA Class I expression on the surface of B cells from healthy donors, as well as patients with rheumatoid arthritis and systemic lupus erythematosus." (PMID 41528734, 2026). "Over follow-up, many CCD cases improved; however, in time-to-discharge analyses, higher IL-23, baseline rheumatoid arthritis, and higher VAS were associated with persistence, whereas higher FGF-2 and IL-4, arthrosis, and anti-CHIKV IgG were associated with earlier resolution." (PMID 41997930, 2026). "In contrast, the 2,311 ligand-receptor DEG-associated canonical pathways were related to activating immune responses, including pathways involving macrophages, fibroblasts, and endothelial cells in rheumatoid arthritis, wound healing signaling, interleukin-4 and −13, and preeclampsia." (PMID 41292920, 2025). "Additionally, HSP60 has been shown to prevent inflammation-induced cell death in rheumatoid arthritis (RA) by promoting the secretion of anti-inflammatory cytokines IL-4 and IL-10 at the site of inflammation in the bone." (PMID 38791521, 2024). "The probability of developing rheumatoid arthritis illness was not correlated with the IL-4 (590 C/T) or IL-6 (174 G/C) gene polymorphisms in this study." (PMID 38344692, 2024). "Furthermore, campesterol stimulates the production of anti-inflammatory interleukin-4 (IL-4) and induces homeostasis of blood chemistry, subsequently alleviating the severity of symptoms in rheumatoid arthritis patients." (PMID 39459282, 2024). "Decreased concentrations of IL-4 have been documented in patients with rheumatoid arthritis who express the TT genotype for the rs2243250 SNP, suggesting that the T allele may function as a biomarker for the intensely inflammatory disease." (PMID 39066175, 2024). "L. fermentum PC1 has a treatment potential against rheumatoid arthritis in the murine model of collagen-induced arthritis through the attenuation of proinflammatory cytokine IL-12 and the augmentation of anti-inflammatory cytokines IL-4 and IL-10." (PMID 35601147, 2022). "The reduction in IL-4 gingival levels may reduce the periodontal breakdown as well as the progression of rheumatoid arthritis." (PMID 30281626, 2018). "Genetic polymorphisms of IL-4 and its signaling downstream element, STAT6, are also related to systemic lupus erythematosus (SLE) in humans, and increased plasma IL-4 can be detected in patients with SLE or rheumatoid arthritis." (PMID 29184551, 2017). "Moreover, in patients with rheumatoid arthritis, IL4 inhibits VEGF production in synovial fibroblasts." (PMID 26437765, 2015). "Given their capacity to produce a variety of cytokines (IL4, IL21 and IFNγ), their association with ACPA positive RA and their presence in the synovium, we suggest an important role of double positive T cells in the pathogenesis of rheumatoid arthritis." (PMID 24667579, 2014). "However, IL-4 protein and mRNA are hardly detected in synovial fluid and synovium of rheumatoid arthritis patients." (PMID 15743487, 2005). "IL-4 and IL-10 have been tested for their anti-inflammatory and chondroprotectiveeffects for the treatment of rheumatoid arthritis (RA); however, results wereinconsistent." (PMID 35549461, 2022). "Rheumatoid arthritis (RA) animal study proposed that MA can effectively stimulate adaptive immune cytokines, such as IL-4 and IL-13, to repair RA damage." (PMID 36712435, 2022). "In PBMC from treatment-naive patients with early rheumatoid arthritis (RA), reduced IL-17A and increased IL-4 levels have been observed in the presence of 1α,25(OH)2D3." (PMID 25071589, 2014). "A number of diseases, including Alzheimer's disease, systemic lupus erythematosus and rheumatoid arthritis, have been associated with changes in the phenotypic and functional characteristics of monocyte-derived DCs (i.e. CD14+ monocytes cultured in the presence of GM-CSF and IL-4 alone)." (PMID 21933242, 2012).
rheumatoid arthritis (continued). "Activating CAP with nicotine reduced the expression of Th17-related IL-17 and Ror-γ, increased expression of Th2-related IL-4 and Gata3, and attenuated the inflammatory response in a murine collagen-induced arthritis (CIA) model of rheumatoid arthritis." (PMID 33380272, 2021). "There was profound increment of interleukin 4 (IL-4), IL-5, and clusterin (P < 0.001) in the salivary proteome of 48 patients with pSS, compared to controls without pSS including 12 patients with rheumatoid arthritis (RA) and 12 healthy individuals." (PMID 26362815, 2015). "For example, Th1 and Th2 cells inhibit osteoclastogenesis through the production of IFN-γ and IL-4, while Th17 cells induce osteoclast formation and osteolysis in rheumatoid arthritis (RA) via the IL-17-mediated induction of RANKL expression on synovial fibroblasts." (PMID 23762088, 2013). "Increased levels of IL-4, IL-6, TNF-α, IL-10, and IL-17 have been reported in rheumatoid arthritis." (PMID 37111383, 2023). "The scientific group discovered via correlation analysis a negative relationship between levels of IL-4 and the Disease Activity Score-28 for Rheumatoid Arthritis (DAS28-ESR)." (PMID 35269633, 2022). "Previous studies have linked CXCR6 expression by CD4+ and CD8+ T cells to IFN-γ but not IL-4 expression in graft-versus-host-induced hepatitis and rheumatoid arthritis." (PMID 23840334, 2013). "In patients with OA, the immunoexpression levels of TNF-α, IL-1β, IL-7, MMP-1, MMP-2, and MMP-3 were significantly higher in patients with active rheumatoid arthritis (RA), whereas the immunoexpression levels of IL-1, IL-2, IL-4, IL-6, IL-15, IL-18, and MMP-3 were not statistically different." (PMID 40004793, 2025). "The slight decrease observed in IL-4 after SO intake was also observed in a clinical trial conducted in 78 patients after administration of 2.5 g/day of conjugated linoleic acid (CLA), 400 mg/day of vitamin E, or their mixture in adults with rheumatoid arthritis." (PMID 36235579, 2022). "Additionally, IL-4 has been shown to increase VEGF levels in fibroblast-like synoviocytes when applied alone, but portrayed an anti-angiogenic effect in the presence of transforming growth factor (TGF)-β, by inhibiting the VEGF production, in the study of patients with rheumatoid arthritis." (PMID 31419243, 2019).
food allergy (88 papers, 2009 to 2025). Gastrointestinal disturbances, skin eruptions, or shock due to allergic reactions to allergens in food. "Enhanced Th2 immune responses are associated with food allergies, with IL-4 directing Th2 cell development." (PMID 38502006, 2025). "Next, to better understand the IL-4 gene dosage effect we observed on the PN-specific IgE response, we tested the effect of the loss of 50% of IL-4 expression on IgE and IgG1 in our food allergy model using a different approach." (PMID 39377224, 2024). "Chatila and colleagues showed that IL-4–expressing Tregs develop in a food allergy model based on an activating mutation in the Il4ra gene and that the IL-4 expressed by these Tregs was critical for the IgE response." (PMID 39377224, 2024). "Overall, our data show that the IgE response, but not the IgG1 response, is extremely sensitive to even partial loss of IL-4 during the food allergy response." (PMID 39377224, 2024). "It has been appreciated for many years that food allergy was associated with an allergen-specific type 2 cytokine profile, defined by production of IL-4, IL-5, and IL-13 from CD4+ T cells." (PMID 36880703, 2023). "Mice with susceptibility to food allergy due to a gain-of-function IL-4R have an abundance not only of conventional Th2 cells but also Tregs producing IL-4." (PMID 36880703, 2023). "IL-4, and IL-13 are associated with humoral responses, and are drivers of inflammation in atopy and food allergies." (PMID 36830973, 2023). "Food allergy is often associated with Th2-skewed immune responses; IL-4 as a marker of Th2 cells promotes IgE production by B cells, while Th1 cells’ cytokine IFN-γ can inhibit Th2 cells’ function." (PMID 36238281, 2022). "Food allergy is associated with the dysregulation of Th2 cytokines, such as IL-4 and IL-10, suggesting that the Th2 response is critical in food allergy." (PMID 34650564, 2021). "Further, food allergy was associated with higher serum IL-4 concentrations in these patients." (PMID 41005294, 2025). "Deletion of IL-4 under the Foxp3 promoter could eliminate susceptibility to food allergy, despite the fact that the mice still had conventional CD4+ type 2 T cells." (PMID 36880703, 2023). "We examined the relationship between S. aureus skin colonization, serum IL-4 concentration, and food allergy in a cohort of 50 patients with AD." (PMID 41005294, 2025). "The key cytokines in food allergy—interleukin‐4 (IL‐4), IL‐5, and IL‐13—operate in peripheral tissues upon inflammatory stimuli." (PMID 40730516, 2025). "We found elevated serum IL-4 concentrations in AD patients with S. aureus skin colonization and food allergy." (PMID 41005294, 2025). "These interactions demonstrate that genetic susceptibility in Th2 pathway genes (IL4R, IL-4, IL13) dramatically amplifies food allergy risk under vitamin D deficiency, while MS4A2 variants modulate vitamin D’s protective effects." (PMID 40927566, 2025). "Genetic susceptibility in Th2 pathway genes (IL4R, IL-4, IL13) dramatically amplified food allergy risk under vitamin D deficiency, with AA/GG/CC genotypes conferring 4- to 26-fold increased susceptibility." (PMID 40927566, 2025). "Here, we show that serum IL-4 concentrations are elevated in patients with AD who have S. aureus skin colonization and food allergies." (PMID 41005294, 2025). "The gene–environment interactions we identified reveal a triad of Th2-sensitizing genotypes—IL4R rs1801275 AA, IL-4 rs2243250 CC, and IL13 rs20541 GG—that confer 4- to 26-fold elevated food allergy risk under vitamin D deficiency." (PMID 40927566, 2025). "Receiver operated characteristic (ROC) analysis revealed that among patients with S. aureus skin colonization, an IL-4 concentration of >10.6 pg/mL had a specificity of 84.6% (95% CI: 57.8%–97.3%) and sensitivity of 68.2% (47.3%–83.6%) for food allergy." (PMID 41005294, 2025). "Food allergy was more frequent, and serum IL-4 concentrations were higher in AD patients with S. aureus skin colonization." (PMID 41005294, 2025).